ELMO2 (engulfment and cell motility 2)
Description:
Regulates the activity of DOCK guanine nucleotide exchange factors (GEFs). Acts in association with DOCK1, DOCK2, DOCK4 and CRK. Involved in cytoskeletal rearrangements required for phagocytosis of apoptotic cells and cell motility.
Synonyms: KIAA1834; CED12; ELMO-2; CED-12; FLJ11656; Ced-12A; VMPI
Tractability: PROTAC: ubiquitination databases record sites on it; its protein half-life has been measured.
Gene: Protein-coding gene on chromosome 20 (46,366,047 to 46,432,985, reverse strand). Ensembl gene ENSG00000062598.
Subcellular location: Cytoplasm; Cytoplasm, cytosol; Membrane
Subcellular location (Human Protein Atlas): Cytosol
Pathways (Reactome):
Signal Transduction: PTK6 Regulates RHO GTPases, RAS GTPase and MAP kinases; RHOG GTPase cycle; VEGFA-VEGFR2 Pathway
Disease: FCGR3A-mediated phagocytosis
Immune System: Regulation of actin dynamics for phagocytic cup formation
Gene Ontology:
Molecular function: protein binding; receptor tyrosine kinase binding; guanyl-nucleotide exchange factor activity
Biological process: cell chemotaxis; actin filament organization; cell motility; regulation of vasculogenesis
Cellular component: cytosol; membrane; cytoplasm
Genetic constraint (gnomAD): Loss-of-function variants: 36 observed, 97.79 expected, observed/expected ratio (o/e) 0.37, 90% interval 0.28 to 0.49. The upper end of that interval is the gene's LOEUF score, 0.49, which puts it in group 2 of 6, group 1 being the genes least tolerant of losing a copy. Missense variants: 540 observed, 930.59 expected, observed/expected ratio (o/e) 0.58, 90% interval 0.54 to 0.62. Synonymous variants: 309 observed, 339.5 expected, observed/expected ratio (o/e) 0.91, 90% interval 0.83 to 1.
Homologues: Orthologues: chimpanzee ELMO2 (100% identical), macaque ELMO2 (99% identical), dog ELMO2 (99% identical), pig ELMO2 (99% identical), guinea pig ELMO2 (99% identical), mouse Elmo2 (99% identical), rat Elmo2 (99% identical), rabbit ELMO2 (98% identical), tropical clawed frog elmo2 (89% identical), zebrafish elmo2 (74% identical). Paralogues in human: ELMO1 (76% identical), ELMO3 (50% identical), ELMOD1 (9% identical), ELMOD3 (8% identical), ELMOD2 (7% identical).
Diseases named in the same sentence as ELMO2 in open-access papers:
ELMO2 is named in the same sentence as 20 diseases in open-access papers, as found by Europe PMC text mining. Sharing a sentence is not in itself a finding about the gene and the disease. The quoted sentences say what the papers report.
breast carcinoma (3 papers, 2016 to 2024). "In breast cancer, a similar study also revealed that the knockdown of ELMO2 diminishes breast cancer cell proliferation, which is regulated by the receptor tyrosine kinase Axl through phosphorylating a conserved carboxyl-terminal tyrosine residue of ELMO2." (PMID 27999268, 2016). "Whether ELMO3 in gastric cancer cells serves a similar role as ELMO2 in breast cancer cells needs further investigation." (PMID 30345300, 2018).
Ramon syndrome (3 papers, 2023 to 2025). "ELMO2 codes for a phagocytosis-associated protein, and homozygous mutation in ELMO2 has been linked to Ramon syndrome." (PMID 37026480, 2023). "However, two previous reports described ELMO2 variants in the context of Ramon syndrome (OMIM #266270), as the probands in those studies exhibited seizures and intellectual disability (ID) as well as typical facial features compatible with fibrous dysplasia but also with VMPI." (PMID 39627357, 2025). "The genetic analysis of the original patients was performed in 2018 and implicated a homozygous variant in Engulfment and cell motility gene 2 (ELMO2; MIM 606421) as underlying Ramon syndrome." (PMID 39201553, 2024). "Bi-allelic variants resulting in loss of function of the ELMO2 and TBC1D2B proteins have been reported in Ramon syndrome." (PMID 39201553, 2024). "To date, two genes, ELMO2 and TBC1D2B, have been linked to Ramon syndrome." (PMID 39201553, 2024).
pancreatic cancer (2 papers, 2020 to 2022). "Taken together, our results confirmed the physical association between ELMO2 and G αi2 in pancreatic cancer cells." (PMID 32292657, 2020). "This study aimed to fully understand the function and mechanisms of ELMO2 in pancreatic cancer chemotaxis and metastasis." (PMID 32292657, 2020). "We found that stimulation with CXCL12 induces a noticeable increase in F-actin in pancreatic cancer cells, which can be prevented by ELMO2 knockdown." (PMID 32292657, 2020). "To explore the role played by ELMO2 in the process of cell migration, we initially investigated its expression level in pancreatic cancer cell lines." (PMID 32292657, 2020). "Our results confirmed this finding and demonstrated that a physiologically relevant interaction between ELMO2 and Gαi2 promoted actin polymerization in pancreatic cancer cells." (PMID 32292657, 2020). "ELMO2 knockdown inhibited pancreatic cancer cell chemotaxis, migration, invasion, and F-actin polymerization." (PMID 32292657, 2020). "According to the colocalization analysis performed on a pixel by pixel basis, Gαi2 and ELMO2 were clearly found to co-localize on the plasma membrane after CXCL12 stimulation of pancreatic cancer cells." (PMID 32292657, 2020). "However, the function of ELMO2 in pancreatic cancer progression and metastasis has been poorly investigated." (PMID 32292657, 2020). "Considering these results, ELMO2 may be regarded as a promising target for the treatment of pancreatic cancer metastasis." (PMID 32292657, 2020). "Here, we addressed the role of ELMO2 in chemotaxis and metastasis of pancreatic cancer cells." (PMID 32292657, 2020). "Therefore, ELMO2 is a boosting factor for the migration and metastasis of pancreatic cancer cells." (PMID 32292657, 2020). "Thus, it was reasonable to expect that G αi2 interacts with ELMO2 in pancreatic cancer cells." (PMID 32292657, 2020). "Thus, ELMO2 is a potential therapeutic target for pancreatic cancer." (PMID 32292657, 2020). "Although ELMO2 has not been subject to extensive research in cancer, a recent study has reported that ELMO2 plays an important role in chemotaxis, invasion and migration mediated by CXCL-2 in pancreatic cancer." (PMID 36551595, 2022). "Pancreatic cancer cell lines PANC-1 and AsPC-1 and siRNA-mediated knockdown of ELMO2 were used to determine the effects of ELMO2 on cancer cell chemotaxis, invasion, migration." (PMID 32292657, 2020). "In this study, we showed that ELMO2 knockdown inhibits CXCL12-mediated migration, chemotaxis, adhesion, and invasion of pancreatic cancer cells." (PMID 32292657, 2020). "In this study, we investigated the role of ELMO2 and CXCL12 in pancreatic cancer using cancer cell lines." (PMID 32292657, 2020). "In summary, we showed that ELMO2 plays an essential role in CXCL12-mediated chemotaxis, migration, and invasion of human pancreatic cancer lines." (PMID 32292657, 2020). "Interestingly, when the expression of Gαi2 was suppressed in human pancreatic cancer cell line PANC-1, ELMO2 translocation was substantially reduced, even in the presence of CXCL12 stimulation." (PMID 32292657, 2020). "However, the mechanism by which ELMO2 interaction with its putative partner, Gαi2, affects the process of metastasis has not been investigated in pancreatic cancer." (PMID 32292657, 2020).
vascular malformation (2 papers, 2025). A non-neoplastic disorder that is the result of defects of vascular morphogenesis. "This case of VMOS associated with homozygous ELMO2 mutation highlights the diagnostic and management challenges of rare intraosseous vascular malformations in children." (PMID 41149120, 2025). "Spontaneous bleeding and soft tissue overgrowth are commonly observed in patients with ELMO2-associated intraosseous vascular malformations." (PMID 41149120, 2025). "In the present case, a pediatric patient harboring a homozygous ELMO2 mutation with clinical features consistent with VMOS (Vascular Malformation—Osteolytic Subtype) demonstrated the full spectrum of associated dental and systemic complications." (PMID 41149120, 2025). "Background/Objectives: Vascular Malformation—Osteolytic Subtype (VMOS) is an exceptionally rare autosomal recessive disorder caused by homozygous pathogenic variants in the ELMO2 gene, with fewer than ten genetically confirmed pediatric cases reported worldwide." (PMID 41149120, 2025). "While ELMO2 deficiency has been linked to intraosseous vascular malformations, we would like to hypothesize that loss of ELMO2 functions might also cause a primary disorder of the craniofacial bones." (PMID 39627357, 2025). "Genetic analysis confirmed a homozygous pathogenic variant in the ELMO2 gene, consistent with a diagnosis of VMOS (Vascular Malformation—Primary Intraosseous Subtype)." (PMID 41149120, 2025).
aneurysm (1 paper, 2025). Bulging or ballooning in an area of an artery secondary to arterial wall weakening. "Loss-of-function mutations in ELMO2 cause intraosseous vascular malformation (VMOS), a human disease involving progressive expansion of craniofacial bones in combination with anomalies in blood vessels that emerge from the external carotid artery, as well as aneurysms in the internal carotid artery." (PMID 40456777, 2025).
asthma (1 paper, 2020). "In addition, two genes (ELMO2, WDFY1) were demonstrated to play roles in inflammation response of asthma." (PMID 32948203, 2020).
carotid artery aneurysms (1 paper, 2025). "Here they show that ELMO2 is crucial for vascular development, with knockout mice being nonviable due to carotid artery aneurysms." (PMID 40456777, 2025).
glioblastoma (1 paper, 2018). The most malignant astrocytic tumor (WHO grade IV). "We found that the methylation levels of ELMO1 and ELMO2 were generally low, whereas ELMO3 methylation levels were high, in the glioblastoma samples." (PMID 29495584, 2018). "Among 121 included glioblastoma patients, successful pyrosequencing results were obtained from 113, 104, and 119 of the patient samples for ELMO1, ELMO2, and ELMO3, respectively." (PMID 29495584, 2018). "On the contrary, less is known about the roles of ELMO2 and ELMO3 in glioblastoma." (PMID 29495584, 2018).
influenza (1 paper, 2023). An acute viral infection of the respiratory tract, occurring in isolated cases, in epidemics, or in pandemics; it is caused by serologically different strains of viruses (influenzaviruses) designated A, B, and C, has a 3-day incubation period, and usually lasts for 3 to 10 days. "Additionally, genes involved in cell processes and cytoskeletal structural elements were upregulated in activated cTfh cells compared to resting cells following influenza vaccination: ELMO2, ACTG1, STMN1, ANP32B, UCP2, and HMGB3." (PMID 37063867, 2023).
Insulin resistance (1 paper, 2022). Increased resistance towards insulin, that is, diminished effectiveness of insulin in reducing blood glucose levels. "Furthermore, a lack of RAC1 is associated with insulin resistance in humans and rodents and ELMO2 and RAC1, both regulate the insulin dependent membrane translocation of the glucose transporter 4 (GLUT4) in muscle cells." (PMID 35874819, 2022).
limb-girdle muscular dystrophy type 2B (1 paper, 2022). "Finally, we showed that the dystrophic features of the Dysferlin-null mice, a model of limb-girdle muscular dystrophy type 2B, were reversed when expressing ELMO2 in an open conformation." (PMID 36400788, 2022).
respiratory failure (1 paper, 2022). The significant impairment of gas exchange within the lungs resulting in hypoxia, hypercarbia, or both, to the extent that organ tissue perfusion is severely compromised. "We found that mice lacking both ELMO1 (globally) and ELMO2 (muscle specific) died at birth, and we speculate that this is secondary to respiratory failure as a result of poorly developed muscles." (PMID 36400788, 2022).
type 2 diabetes (1 paper, 2022). "A previous study has shown that the ELMO2 and SLC13A3 genes may also play a role in type 2 diabetes." (PMID 35964005, 2022).
cancer (6 papers, 2016 to 2022). A tumor composed of atypical neoplastic, often pleomorphic cells that invade other tissues. "ELMO1 and ELMO2 are highly expressed in most human cancer tissues, whereas ELMO3 is only found in some cancer tissues, and its function has not been fully clarified in GC." (PMID 30345300, 2018). "On the contrary, this study is, to our knowledge, the first to describe methylation of the ELMO2 promoter in cancer." (PMID 29495584, 2018). "Overexpression of ELMO2 or Gαi2 might force tumor cells to generate more endogenous Gαi2 or ELMO2 to interact with in order to work together for directing migration and invasion of cancer." (PMID 32292657, 2020). "However, the role and regulating mechanism of EMLO3 remains unclear compared with those of ELMO1 and ELMO2, which present unique and overlapping functions in different types of cancer." (PMID 27999268, 2016).
tumor (5 papers, 2018 to 2025). "The possible reason for this was that the decreased expression of ELMO2 reduced the migration capacity of tumor cells." (PMID 32292657, 2020). "In all, the functional experiments showed that AL121899.1 and ELMO2 are two important tumour suppressors in ESCC." (PMID 32164040, 2020). "Upregulated genes were primarily associated with cell adhesion/invasion/metastasis (ELMO2, ADAM9, DLG1, TRPM7), metabolism/mitochondrial function (FAM120A, DARS2), and cellular transport/axonal trafficking (KIF1B, TBC1D5), indicating the presence of tumor microenvironment stress." (PMID 41404060, 2025). "The functions of two tumour suppressor genes (AL121899.1 and ELMO2), identified in the core modules, were further validated using functional experiments." (PMID 32164040, 2020). "The mean ELMO1, ELMO2, and ELMO3 methylation levels in the tumor biopsies were 6.8% (SD 3.9), 3.3% (SD 2.6), and 80.6% (SD 13.0), respectively." (PMID 29495584, 2018). "The promoter methylation levels of ELMO1 and ELMO2 were generally low, whereas ELMO3 methylation levels were high, in the tumor biopsies." (PMID 29495584, 2018).
neurological diseases (1 paper, 2024). "It is possible that Elmo2 and Dock5 also exhibit specificity in certain types of neurological diseases." (PMID 38666924, 2024).
ELMO2 also shares sentences with these, for which no sentence is quoted: fibrous dysplasia (1 paper); gastric cancer (1); Intellectual disability (1); Primary intraosseous vascular malformation (1).